CD74 (CD74 molecule)
Diseases named in the same sentence as CD74 in open-access papers (continued):
Sharing a sentence is not in itself a finding about the gene and the disease.
neurodegenerative disease (12 papers, 2008 to 2025). A disorder of the central nervous system characterized by gradual and progressive loss of neural tissue and neurologic function. "Cluster of differentiation 74 (CD74) was found to be induced in activated microglia also associated with neurodegenerative diseases and aging." (PMID 37695891, 2023). "In our study, the high expression of Aβ and the enhanced interaction of CD74–COPA in the mouse hypothalamus further suggested that ACP cystic fluid may cause pathological changes similar to those observed in neurodegenerative diseases." (PMID 35525962, 2022). "In neurodegenerative diseases like Alzheimer’s, CD74 is also upregulated in microglia and neurons, affecting amyloid-beta processing and tau phosphorylation, thereby contributing to neuroinflammation and degeneration." (PMID 40400029, 2025). "This hypothesis suggests that the CD74–APP interaction is a way for the body to fight neurodegenerative diseases." (PMID 35525962, 2022). "Interestingly, genes associated with the recently characterized neurodegenerative disease-associated phenotype (DAM microglia), such as Clec7a, Csf1, Cd74, Cxcl10 and Cybb, were downregulated in 5xFAD/Gal3KO mice compared to 5xFAD mice." (PMID 31006066, 2019). "There is very little information on the role of CD74 in neurodegenerative diseases." (PMID 18786268, 2008). "Interestingly, we also found that in addition to the upregulated expression of genes related to microglial inflammatory activation (H-2 gene), genes related to neurodegenerative diseases, such as CD74 and APOE, were also upregulated in the hypothalamus of mice in the cystic fluid group." (PMID 35525962, 2022). "Thus, our data which show similarities to gene expression profiles of other inflammatory and neurodegenerative diseases suggest that CD74 may represent an important link between inflammatory stimuli and vasoregression." (PMID 21379381, 2011). "This process was accompanied by increased expression of CLU, a gene involved in cell death and neurodegenerative diseases, and decreased expression of the immune genes HLA-DRA, HLADRB1 and CD74." (PMID 37275903, 2023). "We found for the first time that the cellular interaction of CD74–APP, previously found in neurodegenerative diseases, is significantly strengthened between inflammation activated microglia and hypothalamic neurons." (PMID 35525962, 2022). "This might be combined with drugs that stop the loss of PNN or block the interaction of MIF with its known receptor (CD74) for a therapeutic strategy to treat ALS and other neurodegenerative diseases." (PMID 33339362, 2020).
hematologic malignancies (9 papers, 2014 to 2026). "From a therapeutic perspective, these data are encouraging as STRO-001 is intended to also target rapidly dividing CD74-positive cells in hematological malignancies in a similar manner to normal B cells and monocytes in monkeys." (PMID 30701025, 2018). "We identified CD74, which is known to be overexpressed in hematological malignancies, as one of the factors interfering with Fas-mediated apoptosis." (PMID 25304249, 2014). "Interestingly, the anti-CD74 drug milatuzumab has been evaluated in hematological diseases with promising results so far." (PMID 37744332, 2023).
cardiovascular diseases (8 papers, 2018 to 2025). "In vessels, CD74 is expressed at increased levels in plaques and peripheral blood mononuclear cells from patients with carotid stenosis and was associated with intima–media thickness in subjects free from clinical cardiovascular diseases." (PMID 38732029, 2024). "The role of CD74 in cardiovascular disease is significant, with CD74 regulating extracellular cathepsin L activity." (PMID 41439980, 2025). "Our systematic review of the role of CD74 in cardiovascular disease will fill some knowledge gaps in the field." (PMID 36712241, 2022). "In this review, we summarize the structure and main functions of CD74 and then focus on the recent research progress on the role of CD74 in cardiovascular diseases." (PMID 36712241, 2022). "Nevertheless, the role of CD74 in cardiovascular disease remains obscure and needs to be further studied." (PMID 36712241, 2022). "Many studies have revealed that CD74 plays an important role in cardiovascular disease." (PMID 36712241, 2022). "Targeted drug therapies for CD74 in cardiovascular disease remain in urgent need of exploration." (PMID 36712241, 2022). "Therapeutic strategies targeting CD74 may provide additional options for the clinical treatment of multiple cardiovascular diseases." (PMID 36712241, 2022). "CD74 expression was elevated in carotid plaques and peripheral blood mononuclear cells (PBMCs) of patients with carotid stenosis, and correlated with carotid intima-media thickness in subjects without clinical cardiovascular disease." (PMID 36712241, 2022).
kidney diseases (8 papers, 2015 to 2025). "CD74 deficiency may be beneficial for some non-renal diseases, such as liver and heart disease, and deleterious in others, such as vascular injury." (PMID 26441987, 2015). "For example, Cd74 (potential target of lncRNA Gm31284) was considered to regulate renal inflammation in kidney disease." (PMID 33779731, 2021). "This information is useful to design therapeutic strategies aimed at modulating CD74 expression both in kidney disease and outside the kidney, and as well as to design strategies to protect the kidneys from the therapeutic use of anti-CD74 antibodies." (PMID 29924850, 2018). "While MIF has been implicated in glomerular and tubulointerstitial injury, very little is known about D-dopachrome tautomerase (DDT), a second ligand for CD74, in kidney disease." (PMID 29924850, 2018). "CD74 is upregulated in tubular epithelial cells and/or podocytes during diverse human kidney diseases." (PMID 29924850, 2018). "TECs significantly upregulated CD74 in kidney disease patients and kidney-injured mice in vivo." (PMID 37511374, 2023). "However, nephrotoxicity is a potential complication of antitumoral anti-CD74 therapy, if kidney cells express high CD74 levels as observed in patients with kidney disease." (PMID 29924850, 2018). "The CD74 signaling machinery may also be upregulated in kidney disease." (PMID 26441987, 2015). "However, we now show that the expression of CD74 and its ligands MIF and DDT was persistently increased suggesting that TWEAK is one of the drivers of their increased expression in kidney disease." (PMID 29924850, 2018).
adenocarcinoma (5 papers, 2005 to 2023). A common cancer characterized by the presence of malignant glandular cells. "Only matched samples of benign and adenocarcinoma tissue were included in the final analyses (MIF in situ, n = 20; MIF IHC analysis, n = 20; CD74 IHC, n = 18)." (PMID 16000172, 2005).
hematological cancers (4 papers, 2010 to 2022). "It has also been demonstrated that CD74’s cytoplasmic domain binds chromatin and regulates the transcription and expression of genes involved in immune regulation, cell survival, and hematopoietic cancers." (PMID 35208514, 2022). "The surface expression levels of CD74 in hematological cancer cells and some solid tumors correlate with poor prognosis." (PMID 25304249, 2014). "The anti-CD74 mAb milantuzumab is currently being studied in phase I/II studies for hematological cancers and could represent a potential pharmacological candidate for MIF-DDT tailored interventions." (PMID 31752120, 2019).
metabolic disorder (3 papers, 2013 to 2022). "Specifically, C3, Cd74, and Agt expression level was increased (migration of cells function) and they affect the endocrine system disorders, gastrointestinal disease, and metabolic disease functions." (PMID 23874995, 2013).
Bacterial infection (2 papers, 2019). "Atlantic cod lacks the genes for MHC-II, the invariant chain/CD74 (Ii), and CD4+ T cell response, representing a paradigm in the context of adaptive immunity against bacterial infectious diseases." (PMID 31231379, 2019). "In this assay, we evaluated the possible roles of thereceptors CD74 and CXCR4 in the observed monocyte-endothelial cell adhesion.Bacterial infection has been previously observed to increase cell adhesion by8.17-fold." (PMID 30506423, 2019). "In contrast to other teleosts, Atlantic cod (Gadus morhua) has an expanded repertoire of MHC-I and TLR components, but lacks the MHC-II, the invariant chain/CD74, and CD4+ T cell response, essential for production of antibodies and prevention of bacterial infectious diseases." (PMID 31231379, 2019).
brain diseases (2 papers, 2019 to 2024). "The association of CD74 in microglia/macrophages and brain disorders have been recently extended and validated by scRNAseq approaches comparing healthy and brains affected by autoimmune disorders, neurodegeneration or ischemia." (PMID 31244853, 2019). "A novel therapeutic approach utilizing our DRQ construct to inhibit dual effects of MIF and D-DT signaling has the potential to treat all progressive brain diseases involving CD74-dependent neuroinflammatory pathways." (PMID 38178143, 2024).
immune disorders (2 papers, 2022 to 2024). "It is worth mentioning that the enhanced interaction of the “CD74-COPA” ligand pair has been shown to mediate immune disorders and thus promote the progression of multiple tumor diseases." (PMID 39872660, 2024). "In this context, we have been working under the hypothesis that the positive Nef-mediated modulation of CD74 in HIV-infected cells plus MIF overexpression play a relevant role in HIV-mediated immune dysfunction and immunopathogenesis." (PMID 36298774, 2022).
hematological tumors (1 paper, 2012). "B cells of these hematological tumors express the target molecule, CD74, at high levels and internalize it rapidly after milatuzumab binding." (PMID 22404985, 2012). "Targeting CD74 as the invariant chain of major histocompatibility complexes (MHC) became possible by the availability of a specific humanized monoclonal antibody, milatuzumab, which is under investigation in patients with hematological neoplasms." (PMID 22404985, 2012).
inflammation (1 paper, 2020). Aberrant reaction of the microcirculation characterized by movement of fluid and leukocytes from the blood into extravascular tissues. "Because acute intestinal inflammation induces Akt activation, we also investigated Akt signaling in CD74–/– mice during DSS-induced intestinal inflammation." (PMID 32004754, 2020).
CD74 also shares sentences with these, for which no sentence is quoted: autosomal dominant polycystic kidney disease (5 papers); hypophysitis (5); non-Hodgkin lymphoma (5); lung squamous cell carcinoma (3); myocardial infarction (3); rheumatic disease (3); amyloidosis (2); asthma (2); B-cell neoplasm (2); cardiomyopathy (2); cervical squamous cell carcinoma (2); chronic kidney disease (2); colorectal (2); esophageal squamous cell carcinoma (2); gastric tumors (2); gastrointestinal disease (2); infectious disease (2); metastatic tumors (2); renal cell carcinoma (2); urothelial bladder carcinoma (2); acquired immunodeficiency (1); adenoid cystic carcinoma (1); adenoma (1); AIDS (1); allergic disease (1); Amebic Colitis (1); aneurysm (1); antibody deficiency (1); aortic stenosis (1); autism (1).
A further 71 diseases each share a sentence with CD74 in 1 paper.